TIMM17B (translocase of inner mitochondrial membrane 17B)
Description:
Essential component of the TIM23 complex, a complex that mediates the translocation of transit peptide-containing proteins across the mitochondrial inner membrane.
Synonyms: TIM17B; JM3; DXS9822
Tractability: Antibody: UniProt predicts a signal peptide or a membrane-spanning region. PROTAC: ubiquitination databases record sites on it; its protein half-life has been measured.
Gene: Protein-coding gene on chromosome X (48,893,447 to 48,898,143, reverse strand). Ensembl gene ENSG00000126768.
Subcellular location: Mitochondrion inner membrane
Subcellular location (Human Protein Atlas): Microtubules; Mitochondria
Pathways (Reactome):
Protein localization: Mitochondrial protein import
Gene Ontology:
Molecular function: protein binding; protein transmembrane transporter activity
Biological process: intracellular protein transport; protein import into mitochondrial matrix
Cellular component: mitochondrial inner membrane; mitochondrion; TIM23 mitochondrial import inner membrane translocase complex
Homologues: Orthologues: chimpanzee TIMM17B (100% identical), macaque TIMM17B (99% identical), guinea pig TIMM17B (97% identical), mouse Timm17b (96% identical), rabbit TIMM17B (96% identical), rat Timm17b (95% identical), zebrafish timm17b (85% identical), pig TIMM17B (80% identical), tropical clawed frog timm17b (78% identical), Drosophila melanogaster Tim17b (67% identical), Drosophila melanogaster CG1724 (58% identical), Drosophila melanogaster Tim17b2 (56% identical), and 5 more. Paralogues in human: TIMM17A (76% identical).
Diseases named in the same sentence as TIMM17B in open-access papers:
TIMM17B is named in the same sentence as 7 diseases in open-access papers, as found by Europe PMC text mining. Sharing a sentence is not in itself a finding about the gene and the disease. The quoted sentences say what the papers report.
breast carcinoma (1 paper, 2024). "Such a specific behavior of TIMM17A in breast cancer made us question whether the transcription of other components of the TIM23 complex, especially TIMM17B, might be dysregulated in various cancers." (PMID 38837610, 2024).
optic atrophy (1 paper, 2009). A disorder characterized by loss of optic nerve fibers. "For example, the optic atrophy 2 (OPA2) linkage interval contains seven mitochondrial genes that include three known DG of which HSD17B10 is associated with optic atrophy, and three predicted DG of which two genes (NDUFB11, TIMM17B) interact with mitochondrial DG causing optic atrophy." (PMID 19390613, 2009).
tumor (2 papers, 2024 to 2025). "Among these, 3 genes including TIMM17B, NTSE and PCSK5 were significantly down‐regulated in tumour tissues compared to normal controls, which is consistent with prior sequencing results." (PMID 41354645, 2025). "Interestingly, we found that the majority of them were markedly upregulated in tumor tissues compared with control samples from unaffected patients and normal tissues adjacent to the tumor, with TIMM23 and TIMM17B exhibiting the most pronounced shift in expression." (PMID 38837610, 2024).
TIMM17B also shares sentences with these, for which no sentence is quoted: cancer (2 papers); cardiac hypertrophy (1); optic atrophy 2 (1); X-linked disease (1).